CLDN9 (claudin 9)
Description:
Plays a major role in tight junction-specific obliteration of the intercellular space, through calcium-independent cell-adhesion activity. (Microbial infection) Acts as a receptor for hepatitis C virus (HCV) entry into hepatic cells.
Synonyms: DFNB116
Tractability: Antibody: UniProt places it where antibodies can reach, with high confidence; its Gene Ontology location is reachable by antibodies, with high confidence; UniProt predicts a signal peptide or a membrane-spanning region.
Gene: Protein-coding gene on chromosome 16 (3,012,923 to 3,014,505, forward strand). Ensembl gene ENSG00000213937.
Subcellular location: Cell junction, tight junction; Cell membrane
Subcellular location (Human Protein Atlas): Cell Junctions; Vesicles
Pathways (Reactome):
Cell-Cell communication: Tight junction interactions
Gene Ontology:
Molecular function: protein binding; virus receptor activity; cell-cell adhesion mediator activity; identical protein binding; structural molecule activity
Biological process: bicellular tight junction assembly; calcium-independent cell-cell adhesion; cell adhesion; symbiont entry into host cell
Cellular component: cell junction; plasma membrane; bicellular tight junction; membrane
Genetic constraint (gnomAD): Loss-of-function variants: 16 observed, 13.91 expected, observed/expected ratio (o/e) 1.15, 90% interval 0.78 to 1.71. The upper end of that interval is the gene's LOEUF score, 1.71, which puts it in group 6 of 6, group 1 being the genes least tolerant of losing a copy. Missense variants: 332 observed, 305.09 expected, observed/expected ratio (o/e) 1.09, 90% interval 0.99 to 1.19. Synonymous variants: 162 observed, 146.91 expected, observed/expected ratio (o/e) 1.1, 90% interval 0.97 to 1.26.
Gene-disease validity (ClinGen):
ClinGen rates the evidence that CLDN9 causes each of these diseases.
hearing loss, autosomal recessive 116 (autosomal recessive): Moderate.
Homologues: Orthologues: chimpanzee CLDN9 (99% identical), guinea pig CLDN9 (98% identical), mouse Cldn9 (97% identical), rat Cldn9 (97% identical), dog CLDN9 (97% identical), pig CLDN9 (96% identical). Paralogues in human: CLDN6 (71% identical), CLDN3 (64% identical), CLDN4 (61% identical), CLDN5 (53% identical), CLDN8 (48% identical), CLDN1 (47% identical), CLDN17 (47% identical), CLDN7 (44% identical), CLDN19 (44% identical), CLDN14 (41% identical), CLDN2 (39% identical), CLDN15 (37% identical), and 10 more.
Diseases named in the same sentence as CLDN9 in open-access papers:
CLDN9 is named in the same sentence as 30 diseases in open-access papers, as found by Europe PMC text mining. Sharing a sentence is not in itself a finding about the gene and the disease. The quoted sentences say what the papers report.
gastric cancer (8 papers, 2012 to 2025). A primary or metastatic malignant neoplasm involving the stomach. "In gastric cancer, strong CLDN9 protein staining in the tissues of diffuse type is associated with high mortality, a finding seemingly replicable in a cell line of gastric cancer." (PMID 38137355, 2023). "The expression of Claudin-9 in the gastric cancer tissue has been linked to poor prognosis, however, its transcriptional and epigenetic regulations demand a more comprehensive analysis." (PMID 39296813, 2021). "The increase in Claudin-9 expression in the gastric cancer tumor tissue is associated with an increase in cell proliferation and invasion." (PMID 39296813, 2021). "For example, reports have shown that CLDN2, CLDN7, and CLDN9 contribute to the enhanced invasion and migration of gastric cancer (GC) cells." (PMID 39199633, 2024). "A different analysis showed that the CLDN9 gene was highly methylated and the heat map results showed the transcriptional repression of the CLDN9 gene expression in gastric cancer patients." (PMID 39296813, 2021). "Nevertheless, the prominence of Claudin-9 in relation to its interactions, activation, and role in gastric cancer is poorly described." (PMID 39296813, 2021). "The heat map results of claudin gene methylation showed transcriptional repression of the CLDN9 gene expression in gastric cancer patients." (PMID 39296813, 2021). "The present work aimed to perform a bioinformatics analysis to understand the mechanisms involved in the transcriptional and epigenetic regulation of Claudin-9 and its repercussions in gastric cancer." (PMID 39296813, 2021). "ETS1, together with other transcription factors including AP-1, NF-κB, and HNF3β, has binding sites in the promoter of claudin 9 gene, and aberrant activity may lead to deregulation of tight junctions in gastric cancer." (PMID 41425714, 2025). "In addition, the high expression of MET and CLDN9 may potentially predict the prognosis of gastric cancer patients, whereas the role of TKTL1 remains unclear." (PMID 37980488, 2023).
deafness (7 papers, 2009 to 2023). An inherited or acquired condition characterized by the complete loss of the ability to hear from one or both ears. "Mice harboring a mutation in claudin-9 gene, which is another component of TJ in the organ of Corti, also exhibit severe deafness with progressive degeneration of hair cells." (PMID 25063198, 2014). "Analysis of Cldn9 mutant mice shows that Cldn9 is a paracellular ion permeability barrier for Na+ and K+, and loss of Cldn9 expression in the inner ear disrupts the Na+/K+ barrier and causes deafness." (PMID 21887364, 2011). "Furthermore, a mutation in claudin-9 gene, another claudin member expressed in the organ of Corti, causes a severe deafness in mice." (PMID 25063198, 2014). "The mutations in TRIC, a gene encoding human tricellulin, were reported to be responsible for hereditary deafness DFNB49, and knockin mice mimicking human mutation exhibit deafness associated with progressive hair cell degeneration, as observed in Occ−/−, claudin-14 and claudin-9 mutant mice." (PMID 25063198, 2014). "In this study, we show that claudin-9 deficiency is associated with deafness." (PMID 19696885, 2009). "It should be noted that the deletions in P1 and P3 extend further in the proximal direction and include THOC6 (MIM #613680, Beaulieu-Boycott-Innes Syndrome) and CLDN9 (deafness, autosomal recessive 116, provisional, #619093)." (PMID 40225164, 2023). "Our analysis of nmf329 mice indicates that the genetic defect in claudin-9 leads to deafness, and that a claudin-9-based ion barrier is necessary to protect the basolateral domain of the hair cell from the K+-rich endolymph." (PMID 19696885, 2009). "The Cldn11 gene, which encodes Claudin-11, has not, thus far, been identified as a deafness gene while mutations in the genes encoding Claudin-14 (DFNB29) and Claudin-9 cause autosomal recessive deafness in humans and mice." (PMID 28848383, 2017). "Although no deafness gene has been mapped to human chromosome 16p13 where claudin-9 is located, a large number of deafness loci likely await recognition and mapping." (PMID 19696885, 2009).
endometrial cancer (4 papers, 2020 to 2025). Primary or metastatic malignant neoplasm involving the endometrium (mucous membrane that lines the endometrial cavity). "CLDN9 is associated with aerobic glycolysis (Warburg effect) in gastric and endometrial cancers and is associated with poor prognosis in oesophageal cancer." (PMID 36233808, 2022). "The conclusion from that study was that aberrant CLDN9 expression is a powerful indicator of poor prognosis in endometrial cancer and could be used alongside CLDN6 to identify high-risk patients." (PMID 40687428, 2025). "Given CLDN9’s role in other cancers (e.g., promoting metastasis in lung models), its prognostic value in endometrial cancer aligns with a broader oncogenic function." (PMID 40687428, 2025). "(2022) found that 17.3% of endometrial carcinomas exhibit high CLDN9 protein expression, and these patients had markedly worse 5-year disease-specific survival (62.8%) compared to those with low CLDN9 (87.8%)." (PMID 40687428, 2025). "Likewise, analysis of TCGA endometrial cancer data highlighted CLDN9 as one of few genes predictive of patient survival, a finding validated by immunohistochemical studies." (PMID 40687428, 2025). "CLDN9 has recently been established as a clinically significant marker in endometrial cancer." (PMID 40687428, 2025). "While not extensively studied in cervix, CLDN9’s association with lymphatic invasion in cervical tumors has been noted, paralleling its poor prognostic impact in endometrial cancer." (PMID 40687428, 2025). "CLDN9 has been found to be related to many human malignancies, such as non-Hodgkin's lymphoma, breast cancer, pituitary oncocytomas, laryngeal carcinoma and endometrial cancer, contributing to disease progression and poor prognosis in patients." (PMID 33234735, 2020). "In summary, claudin dysregulation in endometrial cancer is tied to subtype, invasion, and outcome: high CLDN6/CLDN9 confers poor survival, and may also reflect an immune-cold microenvironment analogous to ovarian tumors." (PMID 40687428, 2025).
breast carcinoma (3 papers, 2022 to 2025). "Recent bioinformatic analyses (TCGA) further support CLDN9’s role: breast cancers express significantly higher CLDN9 mRNA than normal tissue and high levels associated with shorter overall survival." (PMID 40687428, 2025). "There is also interest in CLDN4 and CLDN9 as markers of drug resistance; for instance, CLDN9 upregulation in breast cancer was associated with chemotherapy failure, suggesting that targeting CLDN9 or its pathway could resensitize tumors to treatment." (PMID 40687428, 2025). "Patients who died of breast cancer and who developed breast cancer-related incidence had a raised level of the CLDN9 transcript, although these were marginally statistically significant." (PMID 38137355, 2023). "The other highly interesting finding is the highly significant connection between CLDN9 and drug response in breast cancer." (PMID 38137355, 2023). "The present study investigated the role that CLDN9, along with the subcoat proteins, Zonula Occludens (ZOs), plays in clinical breast cancer and subsequent impact on drug response of patients." (PMID 38137355, 2023). "The aim of this part of the study was to ascertain the correlation between CLDN9 expression levels and chemoresistance across various subtypes of breast cancer cells." (PMID 38137355, 2023). "The breast cancer cell lines MDA-MB-231 (HER-2−/ER−/PR−), MCF7 (HER-2−/ER+/PR+) and SKBR3 (HER-2+/ER−/PR−), representing the main molecular subtypes of breast cancers as portraited earlier, were employed to generate the CLDN9 knockdown cell models." (PMID 38137355, 2023). "Breast cancer cell models, representing different molecular subtypes of breast cancer, with differential expression of CLDN9 were created and used to assess the biological impact and response to chemotherapeutic drugs." (PMID 38137355, 2023). "First, we confirmed that both CLDN9 transcript and the CLDN9 protein are seen in human mammary tissues and breast cancer tissues." (PMID 38137355, 2023). "This therefore establishes CLDN9 in combination with ZO-1 and ZO-3 as a significant prognostic indicator for patient survival in breast cancer." (PMID 38137355, 2023). "In a continued effort to establish the role of tight junction and tight junctional proteins in breast cancer, we determined CLDN9 expression in breast cancer." (PMID 38137355, 2023). "High levels of CLDN9 transcripts clearly indicate resistance to chemotherapies in all breast cancer subtypes, including triple-negative breast cancers (TNBC), other than Her-2-positive breast cancers." (PMID 38137355, 2023). "In patients bearing Her-2 breast cancer, CLDN9 appeared to have lost its value in predicting patient response to chemotherapies." (PMID 38137355, 2023). "High levels of CLDN9 in breast cancer present as a potentially significant prognostic indicator for patients with breast cancer who are Her-2-negative." (PMID 38137355, 2023). "Collectively, CLDN9 is a prognostic indicator for breast cancer and a predictor for patient therapeutic response in Her-2-negative breast cancers." (PMID 38137355, 2023). "To corroborate the clinical findings, we established cell models of breast cancer cells with CLDN9 knockdown, based on analyzing the baseline expression levels of CLDN9 in three breast cancer cell lines." (PMID 38137355, 2023). "Here, we also show that expression of CLDN9 is significantly correlated with ZO-1 and ZO-3 and the integrated co-expression of CLDN-9, ZO-1 and ZO-3 markedly improve the prognostic value in breast cancer." (PMID 38137355, 2023). "CLDN9 transcript levels have a significant impact on breast cancers and patient responses." (PMID 38137355, 2023). "This possibility is partially confirmed in our experiment in that when Her-2 is inhibited by way of therapeutic Her-2 inhibitor and CLDN9 is reduced by genetic knockdown, we were able to sensitize the otherwise resistant Her-2-positive breast cancer to chemodrugs." (PMID 38137355, 2023).
breast carcinoma (continued). "CLDN9 is expressed in mammary tissues and in breast cancer tissues." (PMID 38137355, 2023). "The brief finding that CLDN9 is also seen in the cytoplasmic regions of breast cancer may contribute to this suggestion." (PMID 38137355, 2023). "Her-2 is a negating factor for the treatment response prediction value of CLDN9 and negating Her-2 and CLDN9 may enhance breast cancer cell response to chemotherapeutic drugs." (PMID 38137355, 2023). "Her-2 is a negating factor for the treatment response prediction value by CLDN9 and negating Her-2 and CLDN9 may enhance breast cancer cellular response to chemotherapeutic drugs." (PMID 38137355, 2023). "At transcript levels, breast tissues express significantly high levels and there is a clear indication that high levels of CLDN9 are associated with poor clinical outcome of the patients; however, this connection is not seen with Her-2-positive breast cancers." (PMID 38137355, 2023). "Breast cancer tissues expressed significantly elevated levels of CLDN9 transcript (p = 0.035)." (PMID 38137355, 2023). "However, in patients with Her-2-positive breast cancers, if there are concurrently low levels of CLDN9, a combination of Her-2 inhibitor and chemotherapies may offer benefits to the patient; a clinical study would be highly valuable to confirm this." (PMID 38137355, 2023). "We further developed cell models expressing differential CLDN9 expression levels and different hormonal receptor status, to confirm that in Her-2-positive breast cancer cells (SKBR3), knockdown of CLDN9 rendered the cells more sensitive to chemodrugs when Her-2 inhibitor is present." (PMID 38137355, 2023). "In this study, we report, for the first time, that claudin-9 (CLDN9) is expressed in mammary tissues and that the increased expression in breast cancer, particularly when co-expressed with its anchorage protein ZO1 and ZO3, forms a significant predictor for the survival of patients." (PMID 38137355, 2023). "In Her-2-negative breast cancers including TNBC breast cancer, high CLDN9 expression generally indicates a likelihood of patient resistance to chemotherapy, which may be reflected in the poor clinical outcome of the patients." (PMID 38137355, 2023).
ovarian carcinoma (3 papers, 2021 to 2025). A malignant neoplasm originating from the surface ovarian epithelium. "In fact, one study identified CLDN6 and CLDN9 as additional CPE receptors in ovarian cancer cell lines." (PMID 40687428, 2025). "More broadly, the oncofetal claudins CLDN6 and CLDN9 (normally silenced in adult tissues) are aberrantly activated in ovarian cancers." (PMID 40687428, 2025). "CLDN9 is a tight junction protein normally limited in adult tissues, but it is expressed in ovarian cancer cells and shares homology with CLDN3/4, meaning it might also bind the C. perfringens enterotoxin." (PMID 40687428, 2025). "In summary, ovarian cancer exhibits a pattern of claudin upregulation (CLDN3, CLDN4, CLDN7, CLDN9) that supports tumor growth, dissemination, and chemoresistance." (PMID 40687428, 2025). "Eight genes were overexpressed in ovarian cancer samples compared with normal tissue samples and included CLDN1, CLDN3, CLDN4, CLDN6, CLDN7, CLDN9, CLDN10, and CLDN16." (PMID 34249076, 2021). "While CLDN9’s functional role in ovarian cancer is not fully elucidated, its presence suggests it might contribute to the malignant phenotype or be exploitable for therapy similarly to CLDN3/4." (PMID 40687428, 2025).
lung carcinoma (2 papers, 2022 to 2025). "Beyond CLDN6, other claudins such as CLDN9 and CLDN12 have also been implicated in lung cancer metastasis." (PMID 40687428, 2025). "In one study, silencing CLDN9 expression in p-3LL lung cancer cells using siRNA significantly reduced their motility and invasive capacity in vitro, and suppressed metastatic potential in vivo." (PMID 40687428, 2025).
breast tumors (1 paper, 2025). "Consistently, CLDN9 is overexpressed in breast tumors, and high CLDN9 correlates with poor clinical outcomes and chemotherapy resistance." (PMID 40687428, 2025).
cervical carcinoma (1 paper, 2021). A carcinoma arising from either the exocervical squamous epithelium or the endocervical glandular epithelium. "Claudin-9 is expressed primarily in the inner ear and is essential for hearing, however, its aberrant expression has been reportedly established in lung cancer, pituitary oncocytoma, and cervical carcinoma." (PMID 39296813, 2021). "Claudin-9 expression is related to the increased metastatic ability of the hepatocytes by disturbing the TyK2/Stat3 signaling pathway, and it has been related to lymphatic metastasis in cervical carcinoma." (PMID 39296813, 2021).
esophageal cancer (1 paper, 2022). A primary or metastatic malignant neoplasm involving the esophagus. "CLDN9 can be employed as a prognostic biomarker for gastric and esophageal cancer." (PMID 35281827, 2022).
gastric adenocarcinoma (1 paper, 2013). "The overexpression of claudin-6, claudin-7, or claudin-9 enhanced the invasive potential of a gastric adenocarcinoma cell line." (PMID 24073219, 2013).
hepatocellular carcinoma (1 paper, 2021). A malignant tumor that arises from hepatocytes. "Additionally, elevated tight junction proteins claudin-9 and claudin-17 stimulate migration and invasion of hepatocellular carcinoma (HCC) (liver cancer) cells through activation of the TYK2/STAT3 pathway." (PMID 34439323, 2021).
Obesity (1 paper, 2023). Accumulation of substantial excess body fat. "The claudin-9 (CLDN9) gene was differentially co-expressed in a study of obesity-associated networks in human subcutaneous adipose tissue." (PMID 37606455, 2023).
pituitary adenomas (1 paper, 2021). "Thus, claudin-9 could potentially be used as a diagnostic and/or prognostic marker or an immunotherapy target for subtypes of pituitary adenomas." (PMID 34737342, 2021).
triple-negative breast carcinoma (1 paper, 2023). An invasive breast carcinoma which is negative for expression of estrogen receptor (ER), progesterone receptor (PR), and human epidermal growth factor receptor 2 (HER2). "CLDN9 connection to chemoresistance was particularly prominent in patients of ER-positive (ER(+)), Her-2-negative((Her-2(−)), ER(+)/Her-2(−) and triple-negative breast cancers (TNBCs), but not in patients with HER-2-positive tumors." (PMID 38137355, 2023).